LZTS2 (leucine zipper tumor suppressor 2)
Description:
Negative regulator of katanin-mediated microtubule severing and release from the centrosome. Required for central spindle formation and the completion of cytokinesis. May negatively regulate axonal outgrowth by preventing the formation of microtubule bundles that are necessary for transport within the elongating axon. Negative regulator of the Wnt signaling pathway. Represses beta-catenin-mediated transcriptional activation by promoting the nuclear exclusion of beta-catenin.
Synonyms: KIAA1813; LAPSER1
Tractability: Antibody: its Gene Ontology location is reachable by antibodies, with high confidence. PROTAC: ubiquitination databases record sites on it.
Gene: Protein-coding gene on chromosome 10 (100,996,539 to 101,007,852, forward strand). Ensembl gene ENSG00000107816.
Subcellular location: Cytoplasm; Cytoplasm, cytoskeleton, microtubule organizing center, centrosome
Subcellular location (Human Protein Atlas): Cytosol; Plasma membrane
Gene Ontology:
Molecular function: protein binding
Biological process: negative regulation of canonical Wnt signaling pathway; cell division; microtubule severing; mitotic cytokinesis; negative regulation of Wnt signaling pathway; nuclear export; spindle midzone assembly
Cellular component: cytosol; vesicle; centrosome; cytoplasm; midbody
Genetic constraint (gnomAD): Loss-of-function variants: 32 observed, 51.72 expected, observed/expected ratio (o/e) 0.62, 90% interval 0.47 to 0.83. The upper end of that interval is the gene's LOEUF score, 0.83, which puts it in group 3 of 6, group 1 being the genes least tolerant of losing a copy. Missense variants: 792 observed, 868.48 expected, observed/expected ratio (o/e) 0.91, 90% interval 0.86 to 0.97. Synonymous variants: 360 observed, 377.09 expected, observed/expected ratio (o/e) 0.95, 90% interval 0.88 to 1.04.
Homologues: Orthologues: chimpanzee LZTS2 (99% identical), macaque LZTS2 (99% identical), pig LZTS2 (96% identical), dog LZTS2 (95% identical), rabbit LZTS2 (93% identical), mouse Lzts2 (92% identical), rat Lzts2 (91% identical), guinea pig LZTS2 (90% identical), tropical clawed frog lzts2 (54% identical), zebrafish lzts2a (53% identical), zebrafish lzts2b (41% identical), Drosophila melanogaster CG15365 (23% identical), and 1 more. Paralogues in human: LZTS3 (35% identical), LZTS1 (35% identical).
Diseases named in the same sentence as LZTS2 in open-access papers:
LZTS2 is named in the same sentence as 17 diseases in open-access papers, as found by Europe PMC text mining. Sharing a sentence is not in itself a finding about the gene and the disease. The quoted sentences say what the papers report.
prostate carcinoma (5 papers, 2012 to 2022). A carcinoma that arises from epithelial cells of the prostate gland. "Deletion of the leucine zipper tumor suppressor 2 (Lzts2) that negatively regulates the Wnt pathway through β-catenin interactions has also been shown to synergize with Pten mono-allelic loss to induce early tumor onset and accelerate prostate cancer progression relative to single mutants." (PMID 35204808, 2022). "Emerging studies have demonstrated that the expression of LZTS2 is attenuated or even lost in numerous malignant tumors, such as prostate cancer, non-small cell lung cancer (NSCLC) and colon cancer." (PMID 35179718, 2022). "We observed that mice with both Lzts2 and Pten deletion have an earlier onset of prostate carcinomas as well as an accelerated tumor progression compared to mice with Pten or Lzts2 deletion alone." (PMID 28323888, 2017). "Our data demonstrate the biological role of LZTS2 in tumorigenesis, and implicates the loss of both LZTS2 and PTEN as important biological and relevant events that can directly contribute to prostate cancer development and progression." (PMID 28323888, 2017). "In this study, we observed that PTEN and LZTS2 collaboratively enhance the transcriptional activity of ß-catenin in prostate cancer cells." (PMID 28323888, 2017). "Co-expression of PTEN and LZTS2 in prostate cancer cells shows stronger repressive effect on ß-catenin mediated transcription." (PMID 28323888, 2017). "LZTS2 is expressed in testis, prostate, and ovary tissues, and reduced expression of LZTS2 transcripts and proteins has been observed in prostate cancer samples." (PMID 28323888, 2017). "LZTS2 is expressed in human testis, prostate, and ovary tissues, and reduced expression of LZTS2 transcripts and proteins has been observed in prostate cancer tissues." (PMID 28323888, 2017). "Our data presented in this report provide a line of evidence demonstrating combined loss of LZTS2 and PTEN as an important biological event in prostate cancer development and progression." (PMID 28323888, 2017). "Additionally, LZTS2 protein has low expression levels in human prostate cancer cells." (PMID 29499699, 2018). "Moreover, LZTS2 and PTEN deletion frequently co-occur in human malignancies, including prostate cancer." (PMID 35204808, 2022). "As shown in this study, prostate cancer cells co-transfected with both wild type PTEN and LZTS2 expression vectors showed less transcriptional activity of Tcf/ß-catenin than those transfected with either PTEN or LZTS2 alone." (PMID 28323888, 2017).
colorectal cancer (4 papers, 2022 to 2024). A primary or metastatic malignant neoplasm that affects the colon or rectum. "Another DYRK1B interactor is LZTS2, a negative regulator of beta catenin, suggesting its involvement in colorectal cancer." (PMID 35454940, 2022). "Moreover, it reported that the translation of LZTS2 was reduced in colorectal cancer." (PMID 38850524, 2024).
breast carcinoma (3 papers, 2016 to 2023). "Intriguingly, NF-κB activation was found to inhibit β-catenin/TCF activity through upregulation of LZTS2 in colon, liver, and breast cancer cells but downregulate LZTS2 in glioma cells to promote β-catenin/TCF activity, strongly indicating a cell type-specific effect." (PMID 27713747, 2016).
laryngeal squamous cell carcinoma (2 papers, 2018 to 2024). A squamous cell carcinoma that arises from the larynx. "LZTS2 has emerged as a novel prognostic biomarker for clear cell renal cell carcinoma and laryngeal squamous cell carcinoma." (PMID 38850524, 2024). "No studies to date have described methylation of the LZTS2 promoter in human cancers, including LSCC (laryngeal squamous cell carcinoma)." (PMID 29499699, 2018).
lymph node metastases (2 papers, 2018 to 2023). "Next, associations between clinicopathological characteristics (e.g., age, gender, smoking behavior, histological classification, T classification, clinical stage, and lymph node metastases) and LZTS2 promoter methylation rates were further explored." (PMID 29499699, 2018). "Furthermore, LZTS2 methylation levels were elevated in smokers, advanced T classified, and clinically staged patients, as well as in patients with lymph node metastases." (PMID 29499699, 2018). "Additionally, LZTS2 promoter methylation levels were significantly increased in patients with lymph node metastases, advanced clinical stages, and advanced T classifications." (PMID 29499699, 2018).
autism (1 paper, 2023). Persistent deficits in social interaction and communication and interaction as well as a markedly restricted repertoire of activity and interest as well as repetitive patterns of behavior. "Many of these CNVs encompass genes included in the best‐known lists of candidate genes for autism, including CTNNA3 (OMIM #607667), MACROD2 (OMIM #611567), IMMP2L (OMIM #605977), PARK2 (OMIM #600116), LZTS2 (OMIM #610454), and LRP1 (OMIM #107770)." (PMID 37186221, 2023).
major depressive disorder (1 paper, 2025). An episode of depression lasting two or more weeks without an intervening episode of mania. "Further, LZTS2 is associated with major depressive disorder." (PMID 39277688, 2025).
nasopharyngeal carcinoma (1 paper, 2022). A carcinoma arising from the nasopharyngeal epithelium. "LZTS2 (leucine zipper tumor suppressor 2) mediates both carcinogenesis and cancer development, and its predictive value of poor prognosis and treatment response has been demonstrated also for nasopharyngeal carcinoma patients." (PMID 35406495, 2022).
prostate tumor (1 paper, 2017). "To fully investigate the collaborative role of PTEN and LZTS2 in prostate tumor development, we generated a mouse model, in which both floxed Pten and Lzts2 alleles were targeted on chromosome 19." (PMID 28323888, 2017). "Most intriguingly, approximately 10% of prostate tumor samples have been shown to possess both LZTS2 and PTEN deletion." (PMID 28323888, 2017).
tumor (12 papers, 2012 to 2025). "The leucine zipper tumor suppressor 2 (LZTS2) was identified as a tumor susceptibility gene within the 10q24.3 chromosomal region, and is approximately 15Mb from the PTEN locus." (PMID 28323888, 2017). "Multiple lines of evidence suggest that the Lzts2 gene is a tumor susceptibility gene." (PMID 28323888, 2017). "The presence of LZTS2 is crucial for preventing spontaneous tumor development, indicating that LZTS2 exhibits tumor-suppressing effects even in tumor initial phase." (PMID 35179718, 2022). "A xenograft tumor mouse model showed that the miR-9-5p inhibitor upregulates LZTS2 expression and induce nuclear export of β-catenin in TNBC." (PMID 35179718, 2022). "In our study, LZTS2 promoter methylation levels in LSCC tumor and adjacent normal tissues from 96 patients were measured using quantitative methylation-specific polymerase chain reaction (qMSP) assays." (PMID 29499699, 2018). "The qMSP analyses revealed that LZTS2 promoter methylation levels in the LSCC tumor samples were significantly higher than those in paired adjacent healthy tissue samples." (PMID 29499699, 2018). "Immunohistochemical analyses show that atypical and tumor cells from compound mice with both Pten and Lzts2 deletion are mainly composed of prostate luminal epithelial cells and possess higher levels of cytoplasmic and nuclear β-catenin." (PMID 28323888, 2017). "Through these distinct mechanisms, PTEN and LZTS2 collaboratively regulate cellular levels of ß-catenin and act as tumor suppressors to inhibit Wnt/ß-catenin-mediated oncogenic transformation in cells." (PMID 28323888, 2017). "LZTS2, a tumor suppressor, which is transcriptionally regulated by NF-κB, and the modulation of LZTS2 expression affects cell proliferation and tumor growth through the Wnt/β-catenin pathway in various cancer cell lines." (PMID 22973269, 2012). "LZTS2 is known to be a tumor suppressor by negatively regulating the Wnt pathway in CRC." (PMID 41436424, 2025). "LZTS2, a known tumor suppressor, localizes to centrosomes and regulates microtubule severing." (PMID 40521914, 2025). "Furthermore, functional analyses reveal that SPOP hinders the tumor-suppressive effects of LZTS2 on CRC cell proliferation and metastasis, whereas HAUSP enhances LZTS2's anti-tumor activity in CRC cells." (PMID 41436424, 2025). "The removal of LZTS2 enhances vulnerability to tumor development." (PMID 38850524, 2024). "Moreover, the expression level of LZTS2 decreased in tumor tissues from the GSE20916 and GSE3629 datasets, but appeared increased in samples from GSE21815 and GSE89287 datasets and our clinical samples (P < 0.05)." (PMID 37596528, 2023). "LZTS2 is located at human 10q24.31, which is proximate to the site of the classical tumor suppressor PTEN, indicating that LZTS2 might also exert tumor suppressing effects." (PMID 35179718, 2022). "Thus, evidence supports that LZTS2 is a tumor suppressor gene and that aberrant expression contributes to the genesis and development of some tumors." (PMID 29499699, 2018). "Aged Lzts2 null mice also presented with increased spontaneous tumor development." (PMID 28323888, 2017). "As we reported here, we observed accelerated oncogenic transformation and aggressive tumor phenotypes in the prostates of Lzts2LoxP/LoxP-PtenloxP/Wt:PB-Cre4 mice with the deletion of both Pten and Lzts2 genes in comparison to PtenloxP/Wt:PB-Cre4 mice with Pten deletion only." (PMID 28323888, 2017). "In rat cells, the pluripotent tumor suppressor LAPSER1/LZTS2 binds the katanin p80 subunit directly and shares centrosomal and midbody localization with the p80 subunit, and LAPSER1 has been shown to inhibit the microtubule-severing activity of katanin by binding to the p80 subunit." (PMID 24303010, 2013). "Taken together, our findings reveal a novel role for LZTS2 as a negative regulator of CEP135 and centrosomal microtubule nucleation, providing a potential mechanistic link to its tumor suppressor function." (PMID 40521914, 2025).
tumor (continued). "The expression of four TME-related genes (CXCL10, LZTS2, IDO1, and MAB21L2) that predict the TME signature of CRC was validated in four GEO datasets: GSE20916 (145 samples), GSE21815 (141 samples), GSE3629 (121 samples), and GSE89287 (71 samples), which contained normal control and tumor samples." (PMID 37596528, 2023). "Furthermore, low expression of LZTS2 was significantly correlated with unsatisfactory clinical parameters of TNBC patients, including higher TNM stage, larger tumor size and positive lymph node metastasis, indicating that it might act as a tumor-suppressing lncRNA in TNBC." (PMID 35179718, 2022).
cancer (9 papers, 2012 to 2025). A tumor composed of atypical neoplastic, often pleomorphic cells that invade other tissues. "This event has also been analyzed in LSCC, where the LZTS2 methylation profile has been correlated with cancer risk, progression, and prognosis." (PMID 35406495, 2022). "As EMT has promoting effects on numerous malignant behavior of cancer cells, we then detected the effect of the linc00921/miR-9-5p/LZTS2 axis on migration and invasion in HCC-1937 and MDA-MB-231 cells." (PMID 35179718, 2022). "NF-κB activation leads to the inhibition of the complex β-catenin/TCF/LEF by the upregulation of LZTS2 in cancer cells." (PMID 33503974, 2021). "NF-κB activation leads to the diminution of the complex β-catenin/TCF/LEF by the upregulation of LZTS2 in cancer cells." (PMID 33503974, 2021). "Previous studies have shown that LZTS2 cDNA overexpression suppressed cell growth and reduced colony formation rates of several cancer cell lines, including HEK-293T, AT6.2, LNCaP, PC3, TRSUPr1, Rat-1, and U2OS." (PMID 29499699, 2018). "The present data revealed that LZTS2 promoter methylation levels were significantly higher in LSCC cancer tissues when compared to paired adjacent normal tissues (P = 1.37e−06)." (PMID 29499699, 2018). "This discovery may offer new strategies for utilizing LZTS2 as a potential therapeutic target for cancer treatment." (PMID 41436424, 2025). "Recent findings from two separate studies have shown that knockdown of LZTS2 expression sensitizes cells to paclitaxel therapy in addition to antagonizing proliferation of several cancer cell lines by down-regulation of myc and cyclin D1 through engagement of the NF-κB pathway." (PMID 22606253, 2012). "To date, no reports have investigated methylation of the LZTS2 promoter in human cancers, including LSCC." (PMID 29499699, 2018). "Compared with previous studies that investigated the value of TMEscore in other cancers, our study constructed a four-gene TME signature using TMEscore-related genes (CXCL10, LZTS2, IDO1, and MAB21L2), making it easy for clinicians to assess patients who might belong to the TME-H or TME-L signature." (PMID 37596528, 2023).
LZTS2 also shares sentences with these, for which no sentence is quoted: colon cancer (2 papers); clear cell renal cell carcinoma (1); glioma (1); hepatocellular carcinoma (1); Intellectual disability (1); triple-negative breast carcinoma (1).